MTOR (mechanistic target of rapamycin kinase)
Diseases named in the same sentence as MTOR in open-access papers (continued):
Sharing a sentence is not in itself a finding about the gene and the disease.
oral cancer (continued). "Overall, our data suggest that mTOR signaling plays an indispensable role in the proliferation, migration, and survival of oral cancer cells and regulates various immunological functions in oral tumor-bearing hosts." (PMID 38791040, 2024). "Targeted disruption of the PI3K/Akt/mTOR signalling pathway promotes growth inhibition in oral cancer cells." (PMID 39075562, 2024). "Based on our recently published data, Rapamycin, an inhibitor of the mTOR pathway, exhibits selective antitumor activity in oral cancer by inhibiting cell proliferation and inducing cancer cell apoptosis, autophagy, and cellular stress." (PMID 38276004, 2024). "PI3K/AKT/mTOR pathway was identified as one of the most commonly modulated signals in oral cancer, which regulates major cellular and metabolic activity of the cell." (PMID 38774756, 2024). "Further studies are necessary to elucidate an effective and safe clinical setting for mTOR inhibitors and to develop a more personalized medicine for oral cancer treatment." (PMID 38791040, 2024). "We also provided novel data that both saliva and serum miRNAs can interact with mRNA factors through the PI3K/AKT/mTOR pathway in oral cavity cancer, supporting their further evaluation as potential biomarkers or targets for oral cancer therapy." (PMID 38819439, 2024). "In this study, we examined the immunomodulatory effects of mTOR inhibitors on oral cancer via an analysis of both human OSCC cell lines and an oral cancer mouse model." (PMID 38791040, 2024). "This study showed that piperine inhibits the PI3K/Akt/mTOR signaling pathway in oral cancer HSC-3 cells while also inducing apoptosis and reducing cell viability in a concentration-dependent manner." (PMID 37762259, 2023). "The present study identified that PL-induced autophagy is associated with autophagy factors, such as p-mTOR, LC3, and Beclin-1, in oral cancer cell lines." (PMID 37760883, 2023). "Rhein induced reactive oxygen species (ROS) accumulation in oral cancer cells to inhibit the AKT/mTOR signaling pathway." (PMID 37239855, 2023). "Falcarindiol, an Oenanthe javanica-derived compound, induces apoptosis and autophagy of oral cancer cells by inactivating PI3K/AKT/mTOR/p70S6K." (PMID 36139919, 2022). "The results of this study are in agreement with a recent study that showed that the in vivo administration of TQ downregulated the mRNA levels of PI3K, Akt, and mTOR in hamster oral cancer." (PMID 36145344, 2022). "Inhibition of cancer progression by inhibiting PI3K/Akt/mTOR signaling pathway in various cancers such as prostate, bladder, breast and oral cancers." (PMID 35774603, 2022). "Chlorpromazine, an antipsychotic agent, induces G2/M phase arrest and apoptosis via regulation of the PI3K/AKT/mTOR-mediated autophagy pathways in human oral cancer." (PMID 36421461, 2022). "Many decades of study have proven that the protein kinase B (Akt)/mammalian target of rapamycin (mTOR) pathway is substantially elevated in oral cancer." (PMID 35251696, 2022). "The present study demonstrated the downregulation of different components of PI3K/Akt/mTOR pathway in oral cancer cell lines treated with CZE and CIN." (PMID 35774603, 2022). "Our study demonstrated that chrysophanol induces autophagy and interferes with apoptosis via the PI3k/Akt/mTOR pathway in oral cancer cells." (PMID 36676666, 2022). "By contrast, a recent study reported that PI3K/Akt/mTOR inhibition induced oral cancer cell cycle arrest in vitro and in vivo, implying the promotive effect of the PI3K/Akt/mTOR pathway on cell proliferation." (PMID 34948148, 2021). "In conclusion, this study confirmed that PI3K/mTOR signaling is the important target for developing anticancer agents against radioresistant oral cancer cells." (PMID 33471836, 2021). "Resistance to mTOR blockers has also been reported in oral cancer management, but the mechanisms responsible for this therapeutic resistance are still being explored." (PMID 35047986, 2020).
oral cancer (continued). "In oral cancer, K17 induced cell proliferation and migration by stimulating the Akt/mTOR pathway and promoting glucose uptake." (PMID 33324659, 2020). "This study has also revealed the involvement of the AKT/mTOR pathway in NGAL-mediated control of autophagy in oral cancer cells." (PMID 33297472, 2020). "ORAI2 regulates the migration and colonization of oral cancer cells by inhibiting Akt/mTOR/NF-κB signaling pathway." (PMID 33680910, 2020). "The anticancer activity of JIB extract was first found to inhibit oral cancer cell growth by blocking cell cycle progression, repressing Akt/mTOR signaling and triggering cell apoptosis." (PMID 32545807, 2020). "Our results showed that JIB extract not only inhibited oral cancer cell growth and the induction of apoptosis, but also synergized with cisplatin to downregulate the Akt/mTOR pathway and reduce cell regrowth." (PMID 32545807, 2020). "All these studies outlined the AKT/mTOR pathway significance in the molecular landscape of oral cancer initiation and progression." (PMID 33297472, 2020). "Previous studies have shown that Akt inhibition significantly reduces the phosphorylation of mTOR and enhances cell autophagy in human oral cancer CAR cells." (PMID 31475112, 2019). "Several decades of research have established that the protein kinase B (Akt)/mammalian target of rapamycin (mTOR) pathway is highly upregulated in oral cancer and leads to its development." (PMID 31252679, 2019). "Phosphorylated S6, the downstream target of mTOR, was found to be upregulated in epithelial dysplasia and OSCC; it also can serve as a potent diagnostic biomarker for oral cancer." (PMID 29996471, 2018). "Increasing evidences suggest that tobacco components play a key role in the development of oral cancer and are known to regulate the Akt/mTOR pathway." (PMID 29996471, 2018). "Enhanced AKT/mTOR activity is common in oral carcinomas and alterations of the PI3K/Akt/mTOR pathway are found in a large majority of HNSCCs." (PMID 29506489, 2018). "EGFR is a membrane bound tyrosine kinase receptor, which phosphorylates MEK/Erk, STAT3, and mTOR signal molecules for regulation of cell survival and mitosis in many types of malignancy, including oral cancer." (PMID 29212184, 2017). "In summary, this study confirmed that PI3K/AKT/mTOR signaling pathway activation has a role in radioresistance of oral cancers." (PMID 28978144, 2017). "On the contrary, overexpression of hsa-miR-99a distinctly inhibited cell proliferation and induced apoptosis by down-regulating the expression level of IGF1R and mTOR genes in oral cancer cells." (PMID 26933913, 2016). "Akt/mTOR has been established as a key molecular marker and therapeutic target of oral cancer." (PMID 40940957, 2025). "Our findings suggest that targeting the EGFR/mTOR/Mcl-1 axis with afatinib could be a promising therapeutic strategy for oral cancer treatment, particularly in patients with high EGFR and Mcl-1 co-expression." (PMID 38888847, 2025). "In addition, we reviewed in detail the upstream activators and the downstream effectors of PI3K/AKT/mTOR signaling as potential therapeutic targets for oral cancer treatment." (PMID 38774756, 2024). "Thus, various proteins of PI3K/AKT/mTOR pathway were used as therapeutic targets for oral cancer, to design more specific drugs with less off-target toxicity." (PMID 38774756, 2024). "No information on the association of p-mTOR expression with clinical/pathologic variables in canine oral cancer exists so far, to our knowledge, which makes comparisons of the present results difficult." (PMID 35883491, 2022). "We explored PI3K/Akt/mTOR pathway for inhibiting oral cancer." (PMID 35774603, 2022). "The Cancer Genome Atlas (TCGA) and previous studies have shown that the majority of HNCs possess alterations and are activated in the PI3K/AKT/mTOR pathway, which is also involved in physiological metabolism signaling, chemoresistance and radioresistance in oral cancer." (PMID 34299129, 2021).
oral cancer (continued). "In this study, our data indicate that ANLN could also affect the activation of PI3K/mTOR signaling in oral cancer." (PMID 34082790, 2021). "The AKT/mTOR axis is one of the most reported signaling pathways in oral cancer." (PMID 34299129, 2021). "Therefore, AKT, mTOR and GSK3β at the process of carcinogenesis were appreciated as target molecules for the prevention and treatment of oral cancer." (PMID 34644781, 2021). "Therefore, it is of interest to study the molecular docking-based binding of paclitaxel (a FDA approved drug for oral cancer) and its analogues with mTOR." (PMID 34393439, 2021). "Hence, targeting the AKT/mTOR pathway is an effective approach for treating patients with oral cancer, which has also been supported by previous studies." (PMID 34299129, 2021). "Moreover, UA modulates autophagy and apoptosis in oral cancer cells through the Akt-mTOR and NF-κB pathways." (PMID 34512368, 2021). "Moreover, mTOR immunohistochemical analysis in both HPV (-) and HPV-associated HNSCC lesions have highlighted its important role as a molecular target in oral cancer." (PMID 33297472, 2020). "The frequent activation of the PI3K/mTOR pathway in oral cancers and its cancer-driving role may represent a vulnerability that can be targeted therapeutically." (PMID 32370133, 2020). "The mechanism through which LCN2 exerts its anti-tumor effects in oral cancer may be related to a reduction in autophagy mediated through mTOR signaling pathway activation." (PMID 33604288, 2020). "AMPK and Akt/mTOR signaling showed a key role in cisplatin-resistant human oral cancer CAR cells." (PMID 31750884, 2019). "In addition, targeting AMPK and Akt/mTOR signaling can overcome cisplatin resistance in ovarian and oral cancer cells, respectively." (PMID 31475112, 2019). "Thus, our study clearly demonstrates that knockdown of NGAL increases oral cancer cell proliferation, survival, invasion, and migration by upregulating mTOR signalling and suppressing autophagy." (PMID 29996471, 2018). "Thus, from our study, it is evident that downregulation of NGAL activates the mTOR pathway and helps in the progression of oral cancer." (PMID 29996471, 2018). "The mTOR inhibitors can potentially be used as single therapeutic agents, or in combination with RT or chemotherapeutic agents, to obtain synergistic repression of oral cancer." (PMID 27031247, 2016). "Statins have been shown to inhibit the mevalonate, PI3K/AKT, and mTOR pathways in oral cancer." (PMID 26098683, 2015). "In our previous studies, we suggested that chrysophanol-based therapy could mitigate oral cancer progression through the activation of ferroptosis and modulate cell death, mTOR/peroxisome proliferator-activated receptor α (PPAR-α) signaling, and ROS accumulation in an iron-dependent manner." (PMID 40722814, 2025). "Therefore, pharmacological mTOR inhibition may ameliorate the poor response to immunotherapy using ICIs in oral cancer." (PMID 38791040, 2024). "Moreover, several studies have demonstrated the antitumor effect of modulating mTOR signaling using natural and synthetic inhibitors, indicating that the Akt/mTOR pathway may be a promising therapeutic target for oral cancer." (PMID 38791040, 2024). "However, when APP/PS1 combination was compared with APP/PS1 + PE, we identified 772 DEGs, which were found to be enriched in EIF3K and REST transcription factors, both shown to regulate the mTOR signaling pathway in adipocyte yeast and oral cancer cells, respectively." (PMID 39081972, 2023). "Additionally, lycopene appears to inhibit the epithelial–mesenchymal transition in murine CAL-27 oral cancer xenograft model cells, as demonstrated by changes in cadherin activity, and to slow the in vitro motility of CAL-27 and SCC-9 oral cancer cells via regulation of the PI3K/AKT/mTOR signalling." (PMID 35276890, 2022). "In addition, PI3K/AKT/mTOR pathway was sharply inactivated by LQ in oral cancer cells." (PMID 34488535, 2021).
oral cancer (continued). "Therefore, ANLN contributes to the activation of PI3K/mTOR signaling in oral cancer." (PMID 34082790, 2021). "Thus, the PI3K/AKT/mTOR pathway in oral cancer cells is inactivated by high-dose LQ." (PMID 34488535, 2021). "Inhibitors ofPI3K/mTOR signaling could increase the radiosensitivity of oral cancer cells." (PMID 34082790, 2021). "Furthermore, our findings showed that dual a PI3K/mTOR inhibitor could efficiently overcome radioresistance in oral cells and sensitized oral carcinoma cells to IR." (PMID 28978144, 2017). "Because pharmacological inhibition of AMPK could partially proteced cells from A4-induced apoptosis, we rationalize that this AMPK activation acts in concert with the inhibition of Akt/mTOR and the activation of p38 to facilitate apoptosis in A4-treated oral cancer cells." (PMID 27277973, 2016). "In oral cancer cells, CLU overexpression enhances the activation of the AMPK/Akt/mTOR-mediated autophagy pathway, hence promoting cell survival." (PMID 40475773, 2025). "Next, we investigated mTOR and its related proteins to determine the link between EGFR and Mcl-1 signaling by afatinib in oral cancer cell lines." (PMID 38888847, 2025). "Induces apoptosis, inhibits the AKT/mTOR and Raf/MEK/ERK pathways; exhibits selective in vivo anticancer effects against oral cancer." (PMID 39518052, 2024). "Imatinib also inhibited the PI3K/AKT/mTOR signaling pathway and induced OSCC cell apoptosis, demonstrating the potential of imatinib as a treatment for oral cancer." (PMID 38213733, 2024). "Curcumin can stimulate autophagy in oral cancer cells by activating AMPK and suppressing the mTOR pathway." (PMID 39595208, 2024). "Lycopene administration increases E-cadherin expression in oral cancer cells, reducing EMT and promoting apoptosis through the PI3K/AKT/mTOR signaling pathway." (PMID 37859687, 2023). "Rhein exerted anticancer activity in vitro and in vivo by inducing oral cancer cell apoptosis and ROS via the AKT/mTOR signaling pathway in oral cancer." (PMID 37239855, 2023). "Dietary factors utilize different pathways like PI3K/Akt/mTOR/NF-κB signaling, Hippo-TAZ signaling pathway, Notch signaling pathway, mitochondrial pathway, and Sonic Hedgehog pathway in oral cancer." (PMID 37859687, 2023). "Resveratrol appears to influence autophagy, as an alternative mechanism, and apoptosis, affecting oral cancer cell resistance to cisplatin through the AMPK and PI3K/AKT/mTOR pathways." (PMID 37375955, 2023). "In this study, we aimed to confirm piperine-induced apoptosis and autophagy in oral cancer HSC-3 cells and to evaluate the relationship between these processes and the PI3K/Akt/mTOR pathway." (PMID 37762259, 2023). "Falcarindiol also induces apoptosis and autophagy by inactivating PI3K/AKT/mTOR and activating ERK1/2 and p38 in oral cancer cells." (PMID 36139919, 2022). "The present data demonstrated that signaling molecules, including PI3K, PDK1, Akt and mTOR, were regulated by ANLN in oral cancer." (PMID 34082790, 2021). "In oral cancer, a diverse array of pivotal signaling pathways, including the Wnt/β-catenin signaling PI3K/AKT/mTOR pathway and others, have been identified as being frequently genetically altered." (PMID 34063159, 2021). "In normal keratinocytes (HOK), oral abnormally proliferating cells (LEUK1), oral cancer cells (CAL27), and sequence malignant cell lines, ghrelin, GHSR, mTOR, and phospho-mTOR showed the same increasing trend and correlation." (PMID 31750884, 2019). "In oral cancer, KRT17 stimulates the Akt/mTOR pathway and upregulates SLC2A1 and glucose uptake which facilitates tumor growth." (PMID 30214686, 2018). "Compared to a combination of PI3K or mTOR inhibitors and radiation, dual blockade of the PI3K and mTOR kinases significantly improved radiation efficacy in oral cancer and patient-derived OSCC cells." (PMID 28978144, 2017).
oral cancer (continued). "In this study, we used a radioresistant cell line and patient-derived OSCC cells to improve the understanding of radioresistance of oral cancer cells and the role of the PI3K/AKT/mTOR signaling pathway in radiosensitization." (PMID 28978144, 2017). "Those included an mTOR inhibitor (AMPK agonist) and an EGFR inhibitor (gefitinib), two targets that have been previously reported to prevent oral cancer development in the 4-NQO model." (PMID 27027432, 2016). "Several studies including immunotherapeutic strategies and inhibitors of VEGFR, IGF-1R, PI3K/AKT/mTOR and MET have been conducted, being expected in a near future a shift in the management of oral cancer patients towards more personalized treatment." (PMID 27895714, 2016). "We investigated the effects of mTOR and MEK1/2 inhibition on tumor growth and the tumor microenvironment in immunogenic and poorly immunogenic models of murine oral cancer." (PMID 26506415, 2015). "Polyvinylpyrrolidone (PVP)-functionalized carbon-based nanomaterial (CBN/PVP), obtained through the ball milling of fine graphite flakes, exerted a strong cytotoxic effect on oral cancer cells by promoting oxidative stress and modulating the PI3K/Akt/mTOR pathway." (PMID 40137387, 2025). "In previous studies, we used mTOR-specific and dual-targeted PI3K/AKT inhibitors in oral cancer cell lines and found that blocking PI3K/mTOR increased the radiation sensitivity of oral cancer cells and reversed radiation resistance in a resistant strain (OML1-R)." (PMID 39519390, 2024). "CSE1L could also promotes the proliferative and migratory abilities in oral cancer by positively regulating MITF and activating the Akt/mTOR pathway." (PMID 39430746, 2024). "Therefore, analysing the difference between the expressions of Beclin-1 and mTOR in OLK is helpful to determine the process of occurrence and malignant transformation of oral carcinoma." (PMID 38223571, 2023). "Later, it was shown that mTOR inhibition prevented SQC development in HPV16 E6/E7 transgenic mice after 7,12-dimethylbenz[a]anthracene (DMBA) treatment, decreasing the DNA damage, suggesting an important role for mTOR in HPV-positive oral cancers." (PMID 37237486, 2023). "Because the Akt/mTOR pathway is known to negatively regulate autophagosome formation, we next examined the correlation of NEDD8 expression with the protein levels of autophagosome components, e.g., Beclin-1, Atg5 and LC3-I/II, in oral cancer cells." (PMID 36890567, 2023). "Similarly, Jhou and coworkers found that in oral cancer, CPZ reduced levels of phosphorylation of Akt and mTOR, leading to the cell cycle arrest in G2/M phase and inhibition of cell proliferation." (PMID 34262651, 2021). "Considering the hyperactivation of the PI3K/AKT/mTOR pathway in Head and Neck squamous cell carcinoma (HNSCC), targeting this pathway has become a significant approach for oral cancer treatment, where are responsible for in both in therapy resistance and cell proliferation to some extent." (PMID 34299129, 2021). "In oral cancer, PI3K/mTOR signaling also contributes to progression and deterioration." (PMID 34082790, 2021). "In cisplatin-resistant human oral cancer CAR cells, resveratrol activates autophagy via regulating AMPK and Akt/mTOR pathways, by phosphorylating AMPKα on Thr172 and AMPKα and dephosphorylating Akt on Ser473 and mTOR on Ser2448, and ultimately inhibits CAR cell viability." (PMID 34512368, 2021). "Altogether, our study findings preliminarily demonstrate that CTD inhibits proliferation and induces apoptosis of human oral cancer cells by targeting AKT to downregulate the expression of GSK3β, mTOR and TOPK, thus inhibiting cell growth, migration and apoptosis." (PMID 34299129, 2021). "Current molecular depiction has shown that in oral cancer, PTEN/mTOR/AKT/PI3K appears to be the repeatedly dysregulated pathway and is related to chemo- and radiotherapy resistance via autophagy stimulation, angiogenesis and co-activation of linked signaling pathways." (PMID 35047986, 2020).